EGFR (epidermal growth factor receptor)
Diseases named in the same sentence as EGFR in open-access papers (continued):
Sharing a sentence is not in itself a finding about the gene and the disease.
lung cancer (continued). "Acquired resistance to epidermal growth factor receptor tyrosine kinase inhibitors (EGFR-TKI, such as gefitinib) in lung cancer continues to be a major problem." (PMID 36760347, 2023). "In EGFR TKI‐resistant lung cancer cells, the combination of 8PN and TKI synergistically reduced cell malignance, inhibited downstream EGFR pathway signaling, and exerted additive effects on cell death." (PMID 37013960, 2023). "They then examined others cancer cells, including those of melanoma, lung cancer, breast cancer (BC), and colorectal cancer (CRC), and a similar DTC subpopulation was obtained after various drug treatments (cisplatin and EGFR/RAF/MET inhibitors)." (PMID 37638338, 2023). "The epidermal growth factor receptor (EGFR) is one of the first and most prominent driver genes known to promote malignant lung cancer." (PMID 37542131, 2023). "Collectively, we for the first time investigated the effect of the combination of HCPT and CRI on EGFR- and KRAS-mutant lung cancer cells and first synthesised the conjugates of the two drugs." (PMID 36305251, 2023). "A surge of potential therapeutic targets of lung cancer such as ALK, EGFR, BRAF, c-Ros oncogene 1 (ROS1), MET, and RET came to light in the last decade." (PMID 37568796, 2023). "Its inactivation, which is crucial in lung cancer oncogenesis and progression, leads to the upregulation of the PI3K/AKT pathway and increased tumor progression, resulting in poor EGFR-TKI sensitivity in NSCLC patients." (PMID 36835536, 2023). "Additional four fusions have been identified in lung cancer patients: EGFR–TNS3, EGFR–PURB, EGFR–RAD51, KIF5B-EGFR, and EGFR–ZCCHC6." (PMID 38201251, 2023). "In lung cancer studies, TKI resistant mutants of EGFR kinase exhibit lower proliferation than wildtype EGFR58." (PMID 37567965, 2023). "Currently, the third‐generation EGFR‐TKI, osimertinib, is making another breakthrough in lung cancer targeted therapy." (PMID 36380563, 2023). "The HFD lung cancer (LC-HFD) group exhibited significant tumor formation and deterioration, such as higher EGFR activity and proliferation marker expression, compared with the RD lung cancer (LC-RD) group." (PMID 37929799, 2023). "Amivantamab is a human monoclonal IgG1 antibody that targets both EGFR and MET, which are involved in driving tumor growth in lung cancer and activation of the MET pathway through the positive regulation of MET expression." (PMID 37895255, 2023). "Erlotinib, an EGFR TKI, was also the first globally approved targeted therapy for locally advanced or metastatic non–small cell lung cancer (NSCLC)." (PMID 36647832, 2023). "The EGFR, HER2, and HER3 are overexpressed in lung cancer patient tumors, and monoclonal antibodies (mAbs), such as Herceptin against HER2, are used to treat breast cancer patients." (PMID 37508387, 2023). "As EGFR activation is the main driver of lung cancer, the effects of exposure to PM2.5 on EGFR signaling were examined next." (PMID 36975376, 2023). "Collectively, our results highlight the new molecular mechanisms of AICAR that target MUC1-CT and its interactions with EGFR and JAK1 and provide a new therapeutic approach against EGFR-mutant lung cancer." (PMID 36810913, 2023). "As PI3Kβ is an effector of multiple tyrosine kinase activities that can mediate ALK inhibitor resistance, including EGFR, the co‐targeting of PI3Kβ and ALK offers promise as a treatment for ALK‐rearranged lung cancer." (PMID 36423211, 2023). "The results showed that the mRNA expressions of AKT1, EGFR and IGF1R were upregulated in lung cancer tissues, while the expression of PI3KR1 was downregulated compared with normal lung tissues." (PMID 37533633, 2023).
lung cancer (continued). "Treatment of lung cancer cells with inhibitors of KRAS, EGFR or ALK results in caspase-3-regulated activation of GSDME, thereby increasing the anticancer efficacy of these drugs." (PMID 36920176, 2023). "Since the first experiments targeting epidermal growth factor receptor (EGFR), targeted therapy has begun a new chapter based on an actionable molecular alteration in lung cancers." (PMID 37897649, 2023). "One of its categories, Amivantamab (anti-EGFR, anti-MET), is now approved for lung cancer treatment." (PMID 36810079, 2023). "Currently, the longest OS of EGFR mutant lung cancer patients treated by single agent EGFR-TKI is 38.6 month from the FLAURA study which proved the concept and the clinical benefit of EGFR-TKI as the first-line treatment." (PMID 36895484, 2023). "Thus, in vitro recapitulation of the tumorigenic role of FAF1 may be insufficient when considering a variety of lung cancer cells, for example, with or without EGFR mutation." (PMID 37999107, 2023). "Exon 20 (ex20) in-frame insertions or duplications (ins/dup) in epidermal growth factor receptor (EGFR) and its analog erb-b2 receptor tyrosine kinase 2 (ERBB2) are each detected in 1.5% of non–small cell lung cancer (NSCLC)." (PMID 37284196, 2023). "There is thus a need for alternative therapeutic solutions to enhance the efficacy of EGFR TKIs and reduce the occurrence of TKI resistance in lung cancer treatment." (PMID 37013960, 2023). "Our current results on the negative regulation of EGFR stability through the cooperation of HUWE1 and JMJD5 provide further insight into the complex role of HUWE1 in lung cancer progression." (PMID 37813845, 2023). "They demonstrated that its recombinant version, rLZ-8, induced cycle arrest and apoptosis by downregulating the expression of EGFR and inhibiting EGFR downstream effectors, AKT and ERK1/2 in lung cancer cells." (PMID 37368660, 2023). "In lung cancer, PAK1 promotes inhibitors resistant to tyrosine kinase (Gefitinib and Erlotininb) in both wild-type EGFR and mutant cells." (PMID 36830998, 2023). "To evaluate the efficacy of EGFR-TKIs in EGFR-positive lung cancer patients, we included 160 LUAD, 52 ASC, and 65 LUSC patients who were treated with any EGFR-TKI monotherapy or combination therapies in the clinic." (PMID 37634047, 2023). "This study describes epidermal growth factor receptor (EGFR) testing and overall survival among patients with early‐stage (I‐IIIA) non‐small cell lung cancer (NSCLC) in Denmark." (PMID 35719062, 2023). "For instance, Chinese herbal medicine seemed to exhibit clinical effectiveness on the treatment of epidermal growth factor receptor (EGFR) inhibitor-induced skin rash in patients with cancer, among which were patients with lung cancer." (PMID 37760483, 2023). "However, while these observations are compatible with the involvement of sex steroid hormones, the interaction between PAHs and ER in lung cancer development remains elusive, and AhR-ER crosstalk has so far not been explored in lung cells with EGFR driver mutations." (PMID 37696458, 2023). "In primary lung cancer, a retrospective study found KRAS-mutant tumors had a significantly higher PD-L1 expression, high CD8+T cells infiltration and higher TMB than EGFR-mutant tumors." (PMID 37065830, 2023). "Here, we report that Laminin-5γ-2 (LAMC2) retained high oncogenic capacity in lung cancer, silencing LAMC2 inhibited EGFR-induced cell proliferation and tumor growth in vivo." (PMID 37542131, 2023). "It was previously demonstrated that in non‐small cell lung cancer cells, MET overexpression upregulated EGFR downstream signalling and the use of both EGFR/HER2 and MET tyrosine kinase inhibitors led to a maximal growth inhibition." (PMID 37679999, 2023). "Here, higher hsp70 expression is correlated with longer survival in EGFR-mutant LUAD patients treated with TKI, suggesting a tumor-suppressive role of hsp70 in lung cancer patients." (PMID 37178919, 2023).
lung cancer (continued). "Considering the importance of EGFR as a therapeutic target in lung cancer, we seek to determine potential links between GRP78 and EGFR." (PMID 37487081, 2023). "In the clinic, EGFR-positive LUSC patients have benefited from first-line TKI treatment, highlighting the importance of molecular testing in all lung cancer subtypes to facilitate decision-making." (PMID 37634047, 2023). "Its anti-neoplastic effects were also explained by downregulating the MVA pathway and inhibiting the expression of EGFR, hence suppressing the Ras/Raf/MEK/ERK signal cascade and inducing the apoptosis of lung cancer cells." (PMID 36661704, 2023). "In the present study, using lung cancer cell lines and other cell model systems, we find that GRP78 knockdown in lung cancer led to a reduction in EGFR mRNA level and surprisingly, the regulation is at the transcriptional level." (PMID 37487081, 2023). "The expression of EGFR and IGF1R was also significantly higher in lung cancer tissues than in normal tissues." (PMID 37880793, 2023). "In the treatment of lung cancer, one of the molecular targets is EGFR/ERBB1, belonging to the RTK (receptor tyrosine kinases) family, and Met/HGF, also known as hepatocyte growth factor." (PMID 37373500, 2023). "To determine the expression levels of EGFR and DR4/5 (TNFRSF10A/B) in lung cancers, we analyzed their transcriptional levels in the major 2 histological sub-types NSCLC and SCLC (small cell lung cancer; cancer cell line encyclopedia-TCGA database)." (PMID 37311043, 2023). "A study reported that the blockade of EGFR by afatinib resulted in decreased STAT1 and IRF-1 levels, and disabled the IFN-γ-STAT1-mediated PD-L1 axis in vitro and in vivo for oral cancer and lung cancer." (PMID 37759950, 2023). "In this study, on multiple lung cancer cells, ISL reduced the phosphorylation and catalytic activity of EGFR downstream kinases such as Akt and Erk1/2." (PMID 37373500, 2023). "The effect of the combination of 10-Hydroxycamptothecin (HCPT) and crizotinib (CRI) on EGFR- and KRAS-mutant lung cancer cells was investigated and the conjugates of the two drugs were synthesised." (PMID 36305251, 2023). "In lung cancer, a particular subset of CAF: CD200-positive CAF was uncovered to elevate the sensitivity of cancer cells to EGFR-tyrosine kinase inhibitor (EGFR-TKI), gefitinib, and the sensitizing potential was deprived when CD200 was knocked out." (PMID 37784082, 2023). "We observed that PM induces an altered progenitor state in EGFR mutant AT2 cells through the macrophage release of IL-1β, which promotes lung cancer." (PMID 37020004, 2023). "With specific respect to the epidermal growth factor receptor (EGFR) Hafner and coworkers described in lung cancer A549 cells a specific phenomenon called endosomal arrest." (PMID 36840822, 2023). "In lung cancer, the most relevant therapeutic targets include ROR1, EGFR, PD-L1, CD80/CD86, mucin 1 (MUC1), mesothelin (MSLN), carcinoembryonic antigen (CEA), prostate stem cell antigen (PSCA) and human epidermal growth factor receptor 2 (HER2)." (PMID 36873868, 2023). "Recently, the combination of osimertinib, an ATP-binding competitive inhibitor of epidermal growth factor receptor (EGFR), with EGFR allosteric inhibitors was reported as a next-generation lung cancer therapeutic strategy." (PMID 37241936, 2023). "In this study, we report for the first time the possible hijacking of EGFR and its related downstream signaling pathways by SARS-CoV-2 Spike 1 protein and its RBD in lung cancer cells (A549)." (PMID 37112680, 2023). "Some preclinical studies have shown that the combination of EGFR and VEGFR inhibitors has an enhanced effect on lung cancer cell lines with the potential to overcome primary or acquired resistance to EGFR inhibitors." (PMID 36910653, 2023).
lung cancer (continued). "CUB domain‐containing protein 1 (CDCP1) contributes to epidermal growth factor receptor (EGFR) tyrosine kinase inhibitor (TKI) resistance by regulating EGFR signaling pathways and is a potential target in lung cancer treatment." (PMID 37013960, 2023). "Second, upon examination of database for gene expression in 207 human lung cancer cell lines, we detected a statistically significant positive correlation between GRP78 and EGFR transcript levels." (PMID 37487081, 2023). "To examine the effect of EGFR and IGF1R on lung cancer cell motility, we performed a wound-healing assay on CL1-5 cells infected with EGFR or IGF1R shRNAs." (PMID 37880793, 2023). "Phage display screening with panitumumab-isolated EGFR mimotopes (P19 and P26) and HSP70-P19/P26 fusion proteins reduced tumor growth in lung cancer models, indicating their potential for anti-EGFR immunotherapy." (PMID 37243023, 2023). "We propose that the dysregulated c-Jun/CNOT3 axis can contribute to EGFR-TKIs resistance and CNOT3 is a potential target to enhance the chemosensitivity of lung cancer cells to EGFR-TKIs and to prevent metastatic progression." (PMID 37919290, 2023). "AICAR represses the MUC1 activity in EGFR-mutant lung cancer, disrupting protein–protein interactions between MUC1-CT and JAK1 and EGFR." (PMID 36810913, 2023). "This increases IL-6 expression stimulating cell proliferation in lung cancer and inhibits tumor suppressor liver kinase B1 (LKB1) in EGFR-positive lung adenocarcinoma tumors." (PMID 36661704, 2023). "To further confirm the gains of PELI1 inhibition in the EGFR-targeting therapy, we performed similar cell viability assays in two lung cancer cell lines NCI-H1650 and NCI-H1975 with oncogenic activations of EGFR." (PMID 36841821, 2023). "For example, in ERBB2-overexpressing EGFR T790M lung cancer, we controlled and degraded ERBB2 and as well degraded EGFR, MET, and YES1 kinases that are known to drive this tumor resistance to drugs." (PMID 37359373, 2023). "In lung cancer, two groups demonstrated direct binding between miR-218 and the 3′UTR region of the EGFR mRNA." (PMID 37088795, 2023). "Combining EGFR inhibition and MET inhibition showed anticancer activity in EGFR‐TKI‐resistant MET‐amplified lung cancers in clinical trials." (PMID 38140788, 2023). "Some exciting target antigens used for generating CAR against lung cancer include MUC-1, CEA, MSLN, HER2, GPC3, ROR1, and EGFR." (PMID 36810079, 2023). "In the current guidelines for the management of patients with non-curatively treated lung cancer, the liquid biopsy has found its way into the routine diagnostics for EGFR-mutated tumors, once the disease has progressed under a non-T790 M-addressing EGFR tyrosine kinase inhibitor." (PMID 36900221, 2023). "Overexpression of EGFR and IGF1R induces lung cancer cell proliferation, migration, invasion, drug resistance, stemness and tumor metastasis." (PMID 37880793, 2023). "In lung cancer, the BTK inhibitor ibrutinib effectively inhibits the proliferation of some epidermal growth factor receptor (EGFR) mutant lung cancer cells by inhibiting the autophosphorylation of EGFR." (PMID 37638060, 2023). "First, we examined the effect of Spike 1 and RBD on the phosphorylation status of EGFR and its related kinases, AKT and ERK1/2, in ACE2-expressing lung cancer cells (A549)." (PMID 37112680, 2023). "PLGA NPs (~ 270 nm with a surface charge of ~ 42 mV) loaded with brigatinib, an epidermal growth factor receptor (EGFR) inhibitor, showed the IC50 of 5.25 μg/ml against lung carcinoma cell line A549." (PMID 38112935, 2023). "Epidermal growth factor receptor (EGFR) has been identified in the exosomes of multiple cancer cells, including lung carcinoma cells, colorectal carcinoma cells, and skin epidermoid carcinoma cells." (PMID 36834471, 2023).
lung cancer (continued). "In the present study, we further disclosed that DCLK1 contributes to the activation of EMT in EGFR-TKI-resistant cells, and silencing of DCLK1 sensitizes lung carcinoma cells to EGFR-TKI by reversing the EMT process." (PMID 37239162, 2023). "One study, performed on lung cancer cells using the CRISPR screen, elucidated the mechanism of action of PBRM1 in resistance to EGFR inhibitors." (PMID 35715750, 2022). "Based on the results of KEYNOTE-158 clinical trial, pembrolizumab has been approved by FDA as the front-line therapy for advanced lung cancer patients who present high PD-L1 expressions (TPS > 50%) and who are diagnosed as EGFR or ALK wild-type." (PMID 35346207, 2022). "In the past decade, advances in epidermal growth factor receptor (EGFR) therapy and anaplastic lymphoma kinase (ALK) therapy have remarkably improved the survival of EGFR positive and ALK positive lung cancer patients." (PMID 35971127, 2022). "The aim of this study was to detect the circulating tumor DNA containing the epidermal growth factor receptor (EGFR) exon 19 deletion, which frequently occurs in lung cancer." (PMID 35591635, 2022). "Targeting epidermal growth factor receptor (EGFR) is one of the important treatments for OSCC, lung cancer and other tumors, and has shown good clinical effects." (PMID 35222283, 2022). "For example, METTL3-mediated m6A modification destabilizes SOCS2 mRNA in HCC and BATF2 mRNA in gastric cancer and promotes the translation of epidermal growth factor receptor (EGFR) and the Hippo pathway effector TAZ in human lung cancer cells." (PMID 35456475, 2022). "In lung cancer, DNAJB1 is required for epidermal growth factor receptor (EGFR) signaling activation by inducing proteasomal degradation of mitogen-inducible gene 6 (MIG6), leading to enhanced proliferation of lung cancer cells." (PMID 36499297, 2022). "Family with sequence similarity 188 member B (FAM188B, a deubiquitinase) prevented degradation in phospho-EGFR, phospho-Src, and phospho-ERK to inhibit anoikis in lung cancer cells." (PMID 36230714, 2022). "Rearrangements of MET and the ErbB family RTKs (EGFR, ERBB2, ERBB3, and ERBB4) in lung cancer are less well documented and mostly as case reports." (PMID 36369474, 2022). "The heterogeneity of lung cancer cells in expressing Src kinase activity and dependence of Src activation in regulation of cell growth may be differentially responsive to Src inhibition and also differentially vulnerable to Src activation and development of EGFR TKI resistance." (PMID 35756605, 2022). "Glutamine blockade with JHU083 enhances the efficacy of an epidermal growth factor receptor (EGFR) peptide vaccine in controlling the development and growth of EGFR‐driven lung cancer." (PMID 35861366, 2022). "TNF inhibition via TNFRSF1A silencing, etanercept, or thalidomide increases sensitivity of lung cancer cells to EGFR-TKIs, whereas TNF overexpression attenuates apoptosis induction by EGFR-TKIs." (PMID 35372081, 2022). "KRAS mutations are mutually exclusive with alterations in other molecular markers such as EGFR, ALK and ROS1, considered genetic drivers of lung cancer development." (PMID 36077640, 2022). "For example, in non‐small cell lung cancer models, XIAP antagonist HM90822B was effective as a monotherapy, particularly in cases with activated EGFR signaling." (PMID 35224804, 2022). "Combined TGF-β and hypoxia treatment in lung cancer cells significantly increases the expression and translocation of NRF2 into the nucleus and the crosstalk between NRF2 and EGFR." (PMID 35625561, 2022). "A cohort of 18 lung cancer patients was treated with EGFR TKI or cytotoxic chemotherapy, and a cohort of 37 colorectal cancer patients was treated with EGFR monoclonal antibody or cytotoxic chemotherapy alone." (PMID 35402275, 2022).